CD4 (CD4 molecule)
Diseases named in the same sentence as CD4 in open-access papers (continued):
Sharing a sentence is not in itself a finding about the gene and the disease.
iron overload (12 papers, 2005 to 2025). "Conversely, iron overload as a result of transfusions in thalassemia is associated with decreases in circulating CD4+ T lymphocytes while expansion of CD8+CD28- T lymphocytes has been associated with iron overload in hemochromatosis." (PMID 20716362, 2010). "High CD4/CD8 ratios appear to precede the development of severe iron overload in persons with hemochromatosis." (PMID 16042809, 2005). "Therefore, this study aims to determine the correlations between iron overload (serum ferritin and transferrin saturation) and specific immune cells (CD4)." (PMID 34239727, 2021). "Iron overload significantly affects T-cells, particularly CD8+ cytotoxic T-cells and CD4+ helper T-cells, by impairing their function and expansion." (PMID 39766056, 2024). "In patients with hereditary hemochromatosis, iron overload leads to an increase in the number and activity of suppressor CD8+ T-cells while reducing the proliferation, numbers, and function of CD4+ helper T-cells, resulting in an elevated CD8+/CD4+ ratio." (PMID 39766056, 2024). "For example, patients with iron overload due to β-thalassemia exhibit increased CD8+ T cells and decreased CD4+ T cells." (PMID 38602575, 2024). "In iron overload cases, serum ferritin showed a moderate positive correlation with CD4+CD25+ (r=0.543) and a weak negative correlation with the percentage of CD8+ cells (r=-0.441), which was not statistically significant." (PMID 36945272, 2023). "Altogether, these results suggest that there is not a consistent relationship of severity of iron overload with CD4/CD8 ratios, blood T-lymphocyte subsets, or abnormal total blood lymphocyte counts in patients with hemochromatosis or in those with iron overload due to other causes." (PMID 16042809, 2005).
joint disease (12 papers, 2014 to 2025). "There are a lot of CD4+ T cells in the rheumatoid synovium, and it is believed that an antigen triggers CD4+ T cell activation, which suggests that T cells have a pathogenic role in this joint disease." (PMID 40786589, 2025). "It was put forward that the increased CD4+ CD28− T-cell population in these patients might be involved in aggravated joint disease, as expanded CD4+ CD28− T-cells have been found to cause a significantly faster progression of joint destruction." (PMID 24967373, 2014). "Moreover, a transfer of splenic CD4+ T cells from CHIKV-infected wild-type mice into T cell receptor-deficient CHIKV-infected mice promoted a severe joint disease in the latter, further illustrating the essential role of CD4+ T cells in the CHIKV-associated joint inflammation." (PMID 30364124, 2018). "While T cells have been shown to control alphavirus-mediated infection and disease, anti-CHIKV CD4+ T cells have also been shown in mice to mediate joint disease." (PMID 37983245, 2023). "Regarding human joint disease, it has been described that RA patients have lower frequencies of both CD4− and CD4+ iNKT cells in peripheral blood compared to healthy controls, and they were skewed toward a Th1 phenotype and a more restricted iNKT-TCR repertoire." (PMID 30008717, 2018). "Although the CD4 T cells recruited into the arthritic lesions are predominantly Th1 biased and CD4 T cells are major drivers of arthropathy, they do not appear to be a major source of mGzmA." (PMID 31993061, 2019). "While CD4+ T cells are also crucial effectors in PsO and PsA pathogenesis, we found that CD8+ T cells are required at the early stages of disease development, because their depletion was sufficient to prevent skin and joint disease, even in the presence of residual CD4+ T cells." (PMID 39114979, 2024). "Interestingly, CD4+ and CD8+ T cells in the feet during the acute phase of disease expressed both IL-17A and IL-17F, indicating that IL-17RA signaling may require binding of both IL-17A and IL-17F isoforms in the context of alphavirus-induced arthropathy." (PMID 35143591, 2022).
malignant glioma (12 papers, 2009 to 2024). A grade III or grade IV glioma arising from the central nervous system. "The CD4+ T cells from astrocytoma patients, the most malignant glioma, express the highest proportion of PD-1 compared with other types." (PMID 27756892, 2017). "To ascertain if PBMC expression of p-STAT-3 correlated with the degree of immune suppression, we directed our attention specifically to the Treg fraction in the CD4 compartment since the Treg fraction is elevated in patients with malignant glioma patients." (PMID 19900287, 2009). "In patients with malignant glioma, the CD4+T-cell count decreased dramatically in the peripheral blood, spleen, and cervical lymph nodes, while Tregs significantly accumulated in the tumor microenvironment; both collectively contributing to the immunosuppressive milieu of the tumor." (PMID 27756892, 2017). "Based on these findings, we speculate that the biological activities of CTLA-4 in malignant glioma are carried out preferentially through the inhibition of CD4+ T cell activity." (PMID 27756892, 2017). "Additionally, we will identify the in vivo role of Th17 cells using IL-17A−/− or Rag1−/− mice with malignant glioma, adoptively transferred CD4+ T cells from IL-17A−/− mice." (PMID 21060663, 2010). "Despite a transient increase in mRNA, type I IFN did not increase SAMHD1 protein expression in primary human dendritic cells, macrophages, or CD4+ T cells, but IFN induced SAMHD1 expression in cell lines such as HEK 293T, HeLa, and U87 malignant glioma." (PMID 31600877, 2019). "Particularly, the ectopic expression of decorin in human malignant glioma cells enhances the alloreactive immune response mediated by CD8+, CD4+ T cells, and NK cells." (PMID 26379028, 2015). "Despite a transient increase in mRNA, type I IFNs did not enhance SAMHD1 protein expression in human primary dendritic cells, macrophages, or CD4+ T cells, but type I IFNs induced SAMHD1 expression in cell lines such as HEK 293T, HeLa, and U87 malignant glioma." (PMID 31600877, 2019).
Myocardial fibrosis (12 papers, 2013 to 2025). "In summary, CD4+ helper T cells affect myocardial fibrosis according to different cellular subpopulations, and their mechanism of action is mainly through their secreted cytokines." (PMID 40881586, 2025). "To determine the role of αSMA+ CD4+ co-expressing cells in myocardial fibrosis, we utilized Fischer rats genetically prone to develop PAH as a model of inducible cardiac fibrosis." (PMID 38001239, 2023). "Experimental and clinical studies have shown that myocardial fibrosis is also related to CD4+ T-cell infiltration." (PMID 37504566, 2023). "CD4+ T-cells dominate in inflammation in the hypertrophied myocardium, acting as a ‘transmission link’ between chronic microvascular inflammation and myocardial fibrosis by secreting cytokines that direct M1/M2 macrophage differentiation." (PMID 37504566, 2023). "Furthermore, CD4+ T cells play a critical role in HF and CVDs by driving chronic inflammation and promoting myocardial fibrosis." (PMID 41472876, 2025). "The main surface marker of suppressor T cells is CD4, and they are divided into cell subpopulations such as Th1, Th2, Th3, Th9, Th17, and T follicular helper cells, among which Th1, Th2, and Th17 are closely related to myocardial fibrosis." (PMID 40881586, 2025). "CD4 + CD25 + regulatory T cells (Tregs) have been recognized to play an important role in maintaining peripheral tolerance and limiting inflammatory disease; furthermore, the depletion of Tregs can aggravate myocardial fibrosis." (PMID 36684582, 2022). "CD4+ Th2-type immune responses, mediated by IL-4, are believed to drive fibrotic process and recent study revealed that TNF-α-Secreting B Cells may contribute to myocardial fibrosis in DCM." (PMID 24023968, 2013).
ulcers (12 papers, 2011 to 2025). "Colon tissues were analyzed for IFN or IL-17 secreting CD4+ T lymphocytes via flow cytometry and lymphocytic infiltration, fibrosis, and ulcers by histopathologic evaluation." (PMID 40472038, 2025). "H. ducreyi ulcers are dominated by neutrophilic infiltrates with accompanying CD4+ and CD8+ T cells." (PMID 36534698, 2022). "CD8+ and CD4+ T-cell densities in the genital skin were maximal at ulcer edge, and considerably lower in regions 1 cm away." (PMID 23606943, 2013). "Overall, there was evidence of an impact of the intervention on detectable lesional HIV-1 RNA after adjusting for ulcer aetiology, size of ulcers, duration of symptoms and CD4 group (aRR = 0.73, 95%CI:0.55–0.98)." (PMID 21799914, 2011). "Pooled data were analysed to estimate the impact of acyclovir on the proportion of ulcers healed seven days after randomisation by HIV/CD4 status, ulcer aetiology, size and duration before presentation; and impact on lesional HIV-1." (PMID 21799914, 2011). "Adjustment for factors potentially associated with ulcer healing rate (GUD aetiology, size of ulcer at baseline, duration before presentation, and HIV/CD4 status) made little difference (adjusted RR (aRR) = 1.08, 95% CI 0.98–1.18)." (PMID 21799914, 2011). "HSV-2 infection increases HIV risk, both in individuals with ulcerative disease where there is long-lasting tissue infiltration of activated CD4 T-cells, and also in asymptomatic men where it induces inflammatory foci and the selective foreskin recruitment of CCR5+ CD4 T-cells." (PMID 28893286, 2017). "Garidisan likely improved the quality of ulcer healing by reducing ICAM-1 expression and modifying the balance of CD3+CD4+ T cells/CD3+CD8+ T cells, Th1/Th2, and their secreted cytokines." (PMID 28928792, 2017). "However, our documentation that macrophages number correlates with the necrosis area and lesion size in E-CL indicates that in addition of CD4+ and CD8+ T cells, macrophages play a role in ulcer development in CL due to L. braziliensis." (PMID 28115669, 2017).
Acute hepatitis (11 papers, 2011 to 2025). Acute hepatic injury resulting from inflammation typically accompanied by increased serum alanine transaminase activity. "For example, chronic infection caused by HCV is characterized by weak cellular immune responses against viral antigens while viral clearance after acute hepatitis or after therapy is associated with strong and multispecific antiviral CD4 and CD8 T-cell responses." (PMID 23144910, 2012). "NPNT is an ECM protein that plays a role in acute hepatitis by promoting infiltration of CD4+ T cells or natural killer T cells through interaction with integrins." (PMID 38603681, 2024). "Additionally, it has been reported that anti–VISTA agonist antibody suppresses CD4+ T cell–mediated acute inflammation in a mouse model of acute hepatitis." (PMID 39745792, 2025). "Since NKT cells initiate acute hepatitis pathology in Con A-challenged mice, the attenuated phenotype in HVEM−/− mice could be associated with other HVEM-expressing liver MNCs, such as CD4+ T cells, in these mice." (PMID 31332204, 2019). "An NS3 specific CD4+ T cell immune response is much stronger and more frequently found in patients who resolve acute hepatitis than in patients who develop chronic infection and this response may be necessary for virus clearance." (PMID 22452828, 2012). "Interestingly, the most frequently targeted region in the core protein, which spanned the sequence LCWGELMTLATWVGVNL (position 60−76) was targeted in 6 out of 15 patients (40%) and contains an immunodominant CD4 T cell epitope often recognized during acute hepatitis." (PMID 23750252, 2013). "Notch signaling enhanced IL-22 production by CD4+ T cells even in absence of STAT3 by stimulation of AhR in a ConA-mediated acute hepatitis model in RBP-J−/− mice." (PMID 27800305, 2016). "In order to elucidate, whether this activation is iNKT cell specific or a general effect on lymphocytes due to increased inflammation during acute hepatitis, we compared the expression of CD38 and CD69 on iNKT cells, as well as on CD4+ and CD8+ T cells longitudinally in each individual patient." (PMID 34905514, 2022). "Acute hepatitis can occur in HIV-infected patients but rarely explains cryptogenic hepatitis, at least in an urban population, regardless of geographic origin and CD4 counts." (PMID 21496215, 2011).
anthrax (11 papers, 2012 to 2022). "It was noteworthy that HLA-DR1 transgenic mice, which were the least susceptible to anthrax challenge, responded to fewer epitopes with a reduced repertoire of CD4+ T cell recognition than the other HLA alleles screened." (PMID 36298436, 2022). "However, HLA class II-related differences in susceptibility to anthrax challenge cannot be a simple question of relative availability of high-affinity HLA class II-binding PA epitopes to activate the CD4+ T cell repertoire." (PMID 36298436, 2022). "The 191–200 PA epitope overlapped one that we have previously identified at the CD4+ T cell level as being strongly recognised in the memory T cell response of a 60-year old intravenous drug-user who survived injection of anthrax-contaminated heroin." (PMID 36298436, 2022). "Analysis of the cohort of agricultural workers, previously infected with cutaneous anthrax, showed robust CD4+ T cell memory to anthrax antigens, in line with the observation that, though occupational exposure is ongoing, reinfection is rarely seen." (PMID 26075052, 2015). "The CD4+ T cell epitopes were incorporated into a peptide subunit vaccine and its protective immunity demonstrated in HLA transgenic mice following live anthrax challenge." (PMID 24788397, 2014). "Consistent with induction of immune dysfunction by GI anthrax infection, PD-1 receptor expression was significantly augmented on colonic CD4+ and CD8+ T cells of infected mice, the transcription of which was also confirmed by gene expression analyses." (PMID 24945934, 2014). "The primary importance of humoral immunity in mediating protection against anthrax has been brought into question by recent studies suggesting that IFNγ producing CD4+ T cells play an important role in long lasting immunity." (PMID 24788397, 2014). "On the other hand, it has been shown that protection against anthrax inhalation by an irradiated spore vaccine depends on cholera toxin adjuvant activity mediated by the induction of CD4+ Th17 cells." (PMID 23383086, 2013). "Our own recent research has shown that LF specific IFNγ producing CD4+ T cells play an important role in generating long lasting immunity to anthrax." (PMID 23162703, 2012). "Heat map representation of the epitope mapping results were observed for positive CD4+ T cell IFNγ ELIspot responses in the human donor cohorts, comprising a total of 9 donors in the cutaneous anthrax (Kayseri) group and 10 donors in the AVP vaccinees (UK) group." (PMID 36298436, 2022). "To identify evolutionary differences associated with anthrax susceptibility in humans, we studied changes in CD4 + T cells between humans and non-human primates." (PMID 34782625, 2021). "Also, in this regard, Altman has reported that patients recovered from cutaneous anthrax, who anecdotally exhibit long-term protection from subsequent infection, show high frequencies of CD4+ T cells in response to PA and LF34." (PMID 29725025, 2018). "Vaccines seeking to incorporate the robust, long-lasting, CD4 T cell immune responses observed in naturally acquired cutaneous anthrax cases may need to elicit a similarly broad spectrum cellular immune response." (PMID 26075052, 2015). "We recently studied the CD4+ T cell immune repertoire in patients from the Kayseri region of Turkey who had become infected with B. anthracis and had been hospitalised for cutaneous anthrax following contact with infected livestock." (PMID 24788397, 2014). "This prompted us to reappraise CD4+ T cell immunity to anthrax LF in detail." (PMID 24788397, 2014). "Extensive allelic polymorphisms observed within the HLA region influence the repertoire of antigenic epitopes presented by MHC class II molecules to CD4 T cells; in order to fully elucidate the cellular immune response to anthrax it is therefore important to define these epitopes." (PMID 23162703, 2012).
anthrax (continued). "Importantly, we were able to quantify CD4+ T cell memory responses in naturally exposed cutaneous anthrax patients and in AVP vaccinees, concluding that the T cell response in the former group was equally strong in response to both PA and LF, while in the latter group the major response was to LF." (PMID 24788397, 2014). "These two LF epitopes, able to stimulate CD4+ T cells at very high frequency and across HLA class II differences are thus highly unusual and of considerable interest both for efforts to understand immunity to anthrax and to design universally stimulatory vaccines." (PMID 24788397, 2014). "The identification of cryptic CD4+ T cell epitopes which may also be involved in initiating a neutralizing antibody response against LF would allow both the humoral and cellular immune system to provide robust protection to anthrax infection following immunization." (PMID 26779161, 2015).
Ataxia (11 papers, 2008 to 2025). Ataxia refers to impaired coordination of voluntary muscle movement. "The improvement of cerebellar ataxia was similar to that observed in the whole CD4-positive cell-injected group." (PMID 37369603, 2023). "As a result, the female NPC1 mice that received CD4-positive T lymphocytes exhibited an improvement of cerebellar ataxia." (PMID 37369603, 2023). "To assess whether disease development in Malt1-PD and -PDT mice was due to the same mechanism, we evaluated cytokine production by CD44+ CD4+ T cells in cervical lymph nodes (cLN) of mice already suffering from ataxia." (PMID 31474984, 2019). "RKl-8 had fewer than 200 CD4+ T cells for almost one year before it died for unknown reasons during exam for acute onset of ataxia." (PMID 18928523, 2008). "In contrast, approximately 40% of the C57BL/6 RAG1-/- mice that obtained CD4+ immune T cells developed a neurological score and the same symptoms as R. typhi-infected C57BL/6 RAG1-/- control mice including tremor and/or ataxia." (PMID 27875529, 2016). "Finally, the development of severe ataxia in Smox/Sat1-dKO mice was accompanied by accumulation of CD3+, CD4+, and CD8+ lymphocytes in the leptomeninges." (PMID 33054763, 2020). "CD4 counts reflected this pattern, with severe depletion (<50 cells/μL) in 28.6% of hyperkinetic, 22.2% of hypokinetic, and 22.2% of ataxia patients, while higher counts (≥200 cells/μL) were more common in hypokinetic (33.3%) than in hyperkinetic (4.8%) or ataxia (not reported in over half)." (PMID 41049318, 2025).